INS (insulin)
Diseases named in the same sentence as INS in open-access papers (continued):
Sharing a sentence is not in itself a finding about the gene and the disease.
Impaired glucose tolerance (continued). "Further studies showed that the overexpression of EDA in mice could aggravate the impaired glucose tolerance induced by HFD fed, while EDA knockdown could improve insulin sensitivity in diabetic mice." (PMID 34858327, 2021). "Taken together, skeletal muscle knockout of Exoc5 resulted in increased fasting glycemia and impaired glucose tolerance, but did not impair a functional insulin signaling pathway activation." (PMID 33647317, 2021). "Our finding is consistent with multiple prior studies demonstrating that fasting insulin levels strongly predict M-value in participants with normoglycemia, impaired glucose tolerance, and non-insulin dependent diabetes." (PMID 34075130, 2021). "Over time, the pancreas is no longer able to support adequate insulin secretion, leading to the development of impaired glucose tolerance and to an established diabetic condition." (PMID 33925459, 2021). "Mice lacking miR-155 fed normal chow exhibit impaired glucose tolerance and decreased insulin sensitivity with unaltered insulin production capacity." (PMID 34287359, 2021). "Those participants who did not maintain an appropriate glycemic control, including impaired glucose tolerance, were treated with insulin therapy (n = 25; 36.8% of the sample)." (PMID 33513843, 2021). "This occurs in the absence of increased insulin demand i.e., impaired glucose tolerance and increased adiposity in both male and female offspring." (PMID 34436455, 2021). "Furthermore, the suppression of insulin has been reported during application of VNS in awake rats, which resulted in elevated fasted blood glucose levels and an impaired glucose tolerance." (PMID 32512650, 2020). "For example, rats or mice injected with streptozotocin (STZ), infused with glucose, or mutated for the leptin receptor show that the diabetic condition during pregnancy leads to impaired glucose tolerance (IGT), impaired insulin secretion, and/or increased insulin resistance in adult offspring." (PMID 31308441, 2019). "Consistently with an impaired glucose tolerance, the F1CA;+/+ males showed lower fasting insulin concentrations before and along the GTT protocol (Supplemental 1d) and lower abilities to normalize glycemia when challenged with exogenous insulin (ITT) compared to F1CT;+/+ males." (PMID 30443025, 2018). "Impaired glucose tolerance involves elevated levels of glucose, insulin, and nonesterified fatty acids (NEFAs) in the circulation." (PMID 29874805, 2018). "A previous study showed that the F2 offspring of F1-GDM fathers with IGT developed impaired glucose tolerance and decreased fasting insulin levels at 8 weeks, without alterations in bodyweight and fasting glucose levels." (PMID 29801514, 2018). "Overall, these results indicated that in young, healthy Asian people, reduced insulin sensitivity can be present without any sign of impaired fasting glucose or impaired glucose tolerance." (PMID 29495492, 2018). "In the present study we did not include stimulated measurements of plasma glucose and insulin, precluding assessment of gut microbiota differences between states of impaired fasting glucose and impaired glucose tolerance." (PMID 29379988, 2018). "During the treatment period, OLZ-treated rats had higher fasting insulin levels and HOMA-IR with mildly impaired glucose tolerance, whereas CLZ-treated rats showed significantly lowered fasting plasma insulin levels and impaired glucose tolerance compared with the control." (PMID 28584269, 2017). "HD fed mice showed increased body weight and impaired glucose tolerance, whereas pyridoxamine administration significantly improved insulin sensitivity, but not body weight, and reduced diet-induced increase in serum creatinine and urine albumin." (PMID 29214163, 2017). "Furthermore, the acute hyperuricemic mice model showed impaired glucose tolerance and insulin tolerance accompanied by increased phospho-IRS1 (Ser307) and inhibited phospho-Akt response to insulin in myocardial tissues." (PMID 26836389, 2016).
Impaired glucose tolerance (continued). "In summary, we have showed that insulin sensitivity is impaired in the MDD patients, together with reductions in the disposition index (i.e., oral DI), resulting in impaired glucose tolerance as manifest by elevated 1-hr glucose values following an oral glucose challenge." (PMID 27274905, 2016). "Chronic administration of olanzapine significantly elevated fasting glucose and insulin levels, impaired glucose tolerance, but did not increase body weight." (PMID 27973621, 2016). "The impaired glucose tolerance in male β-MDM2KO mice was associated with defective GSIS and independent of insulin sensitivity, as determined by insulin tolerance test (ITT)." (PMID 27265727, 2016). "Plasma insulin levels, determined at baseline, 15 and 90 min following glucose load were similar in mice treated by 1 versus control vehicle, suggesting that the impaired glucose tolerance was not attributable to a change in insulin levels." (PMID 26394692, 2015). "While HCL and fasting insulin may correlate, data on its relationship with dynamic/OGTT postload β-cell function in collectives with normal and impaired glucose tolerance was contradictory." (PMID 24732091, 2014). "Conversely, loss of KLF11 function in db/m mice modestly increased blood glucose levels and impaired glucose tolerance, but not insulin tolerance." (PMID 24586865, 2014). "PIK3CA is critical in the insulin transduction pathway and dysfunction of PIK3CA may lead to IR and impaired glucose tolerance, as suggested by evidence from the hepatic Pik3ca knockout mice." (PMID 23826284, 2013). "In a clinical study in obese, impaired glucose tolerance (IGT) subjects, HE3286 significantly increased the frequency of insulin-resistant subjects with improved day 29 insulin-stimulated glucose disposal, increased HDL cholesterol, and decreased day 28 CRP compared to placebo-treated subjects." (PMID 23431246, 2013). "This clinical study aimed to investigate the effects of acacia polyphenol (AP) on glucose and insulin responses to an oral glucose tolerance test (OGTT) in non-diabetic subjects with impaired glucose tolerance (IGT)." (PMID 23837032, 2013). "In a non-randomized experimental trial, smoking acutely impaired glucose tolerance and insulin sensitivity, and increased serum LDL cholesterol, triglyceride, blood pressure, and heart rate." (PMID 21208426, 2011). "Nevertheless, studies on drug-naïve first-episode patients already find impaired glucose tolerance, elevated insulin and metabolic abnormalities that are not related to poor health habits." (PMID 21429189, 2011). "We have, however, previously shown that impaired glucose tolerance have effect only on the glucose responses whereas it does not have effect on insulin, TG nor FFA responses." (PMID 21904606, 2011). "Excluding subjects who had impaired glucose tolerance in the analysis did not have major impact on the glucose nor insulin results (data not shown)." (PMID 21904606, 2011). "Impaired glucose tolerance was coupled with inadequate insulin secretion in vivo, and when considered as a fraction of (the low) islet insulin content, glucose-augmented insulin secretion was not decreased from isolated islets of β-Hrd1–KO mice." (PMID 41252202, 2026). "Increasing evidence has shown that α-HB is an early predictor of IR and impaired glucose tolerance, the combination of α-HB and L-glycerophosphate choline showed similar accuracy to glucose in OGTT assay, and the plasma level of α-HB was negatively correlated with insulin sensitivity." (PMID 38027178, 2023). "Future studies will address the mechanism(s) underlying the sexually dimorphic effects on metabolism (increase in body weight, impaired glucose tolerance, and decreased insulin sensitivity in females, but not in males) upon acute gonadotrope ablation in adults." (PMID 36841874, 2023).
Impaired glucose tolerance (continued). "Overexpression of GLUT4 significantly accelerated glucose transport in transgenic rats with or without insulin stimulation and muscle glucose utilization was also increased, which effectively improved impaired glucose tolerance and reduced blood glucose levels in diabetic rats." (PMID 36770636, 2023). "These authors showed that TrkB.T1 knockout leads to impaired glucose tolerance and insulin secretion in mice, with BDNF acting on TrkB.T1 in pancreatic β-cells to trigger calcium release from intracellular stores that enhances glucose-induced insulin secretion." (PMID 36834709, 2023). "However, impaired glucose tolerance (IGT) was found in both 8-week-old mice of the GDM-F1 group, whose blood glucose level significantly increased at 30 min after injection; along with this, we found increased fasting insulin concentration in GDM-F1 male mice." (PMID 35432202, 2022). "The ORIGIN study in patients with impaired glucose tolerance and early type 2 DM showed that treatment with the insulin-glargine did not increase composite cardiovascular outcomes compared to standard care without insulin." (PMID 35268317, 2022). "In our study, we found that the rs4953361 polymorphism of HIF2a may be associated with elevated BMI and metabolic disorder, especially impaired glucose tolerance and insulin release in infertile women with PCOS, but not UI." (PMID 36157441, 2022). "Importantly, mice lacking Gpr180 showed elevated fasting blood glucose levels and displayed impaired glucose tolerance, although fasting insulin levels were not altered." (PMID 34880217, 2021). "We previously provided genetic evidence for a role for insulin by demonstrating that alpha cell-specific insulin receptor knockout (alphaIRKO) mice exhibit hyperglucagonemia, impaired glucose tolerance, and a lack of suppression of glucagon release in response to insulin stimulation." (PMID 33839150, 2021). "It should be noted that at this age, male (and not female) offspring of high fat diet-fed dams have increased adiposity and impaired glucose tolerance compared to controls, however, the impact on glucose-stimulated insulin secretion in islets was not investigated." (PMID 34436455, 2021). "Thus, on a normal chow diet, male heterozygote knockout mice (aTCF7L2het) exhibited impaired glucose tolerance at 16 weeks (p = 0.03) and increased fat mass (1.4 ± 0.1-fold, p = 0.007) but no changes in insulin secretion." (PMID 33068125, 2021). "The results demonstrated that mice on the high-fat diet increased weight gain and showed higher blood concentrations of glucose, insulin, and leptin, as well as impaired glucose tolerance and pancreatic β-cell function relative to those on the normal control diet." (PMID 33322303, 2020). "This corresponded to elevated blood glucose, but not insulin with the HFS diet alone that was reflected in impaired glucose tolerance in the HFS-fed females compared to the LFD, with the most negative impact on glucose tolerance shown in the HFS + PMI5011 group." (PMID 32726932, 2020). "In addition, IPGTT and ITT results did not indicate impaired glucose tolerance and insulin sensitivity." (PMID 30902099, 2019). "Furthermore, it is reported that HOMA-IR and insulin action do not clearly correlate, particularly in individuals with impaired glucose tolerance." (PMID 29467719, 2018). "However, in this study tumor incidence was not correlated with impaired glucose tolerance or insulin sensitivity determined by acute tests with bolus injections of glucose or insulin." (PMID 26924712, 2016). "28% had decreased insulin sensitivity, but none had impaired glucose tolerance." (PMID 22848584, 2012). "However, the reduced amount of insulin does not result in an impaired glucose tolerance." (PMID 38228886, 2024).
Impaired glucose tolerance (continued). "In addition, previous clinical studies showed that in the OGTT, participants with impaired glucose tolerance are characterized by a significant increase in post-load glucose levels in the late phase (60 to 120 min) but not by a reduction of insulin secretion in the early phase." (PMID 38347961, 2024). "However, at 25 weeks of age, the impaired glucose tolerance was reversible to the response of the control regardless of increased adiposity and body weight pointing towards a compensatory response of the insulin sensitivity or insulin secretion." (PMID 30026488, 2018). "Another study assessing insulin-induced thermogenesis (defined as the percentage of increase in metabolic rate during an insulin/glucose infusion) showed a decrease from subjects without DM (11.7%) to patients with impaired glucose tolerance (7.3%) and finally patients with DM (6.5%)." (PMID 28066773, 2016). "In the present study we show that OF has a negative effect on glucose and insulin tolerance at post-OF, similar to a study in C57B6/J mice treated with VCD which had impaired glucose tolerance at 6 months following VCD injection, but not at 4.5 months." (PMID 41282256, 2025). "In addition, it has been shown that 5-HT can regulate insulin secretory function in beta cells via the 5-HT3 receptor under HFD-induced metabolic stress conditions, which may also be a potential mechanism for 1-MT treatment to rescue the HFD-induced impaired glucose tolerance." (PMID 38816357, 2024). "Nine T1Ab+ patients had variable impaired glucose tolerance (IGT), four had pre-T1D (3 T1Ab+, 1 HLA+), nine had T1Ab+ new-onset T1D not requiring insulin at diagnosis." (PMID 37238410, 2023). "The excessive HFCS–water intake resulted in impaired glucose tolerance due to insulin-secretion defect in OGTT; however, there was no change in the insulin-positive area or Ins1 and Ins2 expression in the pancreas." (PMID 34066196, 2021). "To provide information about carbohydrate metabolism in apneic and non-apneic patients, we analyzed fasting glucose insulin levels, HOMA index, impaired fasting glucose (IFG) and impaired glucose tolerance (IGT)." (PMID 33451031, 2021). "In a previous study, SAT and VAT NRG4 was significantly decreased in patients with impaired glucose tolerance (IGT) and T2D, but this study did not evaluate insulin sensitivity." (PMID 30766490, 2019). "Chronic OLZ treatment induced significant weight gain leading to a higher fasting insulin level and impaired glucose tolerance, whereas CLZ lowered fasting insulin levels and impaired glucose tolerance independent of weight gain." (PMID 28584269, 2017). "Arr3-knockout mice displayed impaired glucose tolerance and insulin secretion; however, GLP-1 amplification of insulin secretion was not affected." (PMID 25191754, 2014). "Interestingly, the expression of FA2H is significantly lower in impaired glucose tolerant (IGT) and T2D islets when the insulin secretion index is significantly suppressed than in non-diabetic islets, indicating potential involvement of FA2H in human β cell functions." (PMID 39442620, 2024).
gestational diabetes (1,117 papers, 2005 to 2026). Carbohydrate intolerance first diagnosed during pregnancy. "The genus Collinsella has been controversially linked to metabolic disturbances, such as gestational diabetes mellitus, increased circulating insulin levels, and low dietary fiber intake." (PMID 41428801, 2026). "We have identified for the first time that a higher fibre intake is associated with reduced requirement for insulin in gestational diabetes." (PMID 39473074, 2025). "Increased insulin concentrations were associated with gestational diabetes (SMD 0.35, 95% CI 0.22, −0.47; P<.001, I2 0%)." (PMID 41019841, 2025). "The clinical data confirmed pre-conceptional overweight as a risk factor in women with insulin-treated gestational diabetes mellitus." (PMID 39384641, 2025). "Changes to lipid metabolism have been suggested to be responsible for disruption of insulin sensitivity in a mouse model of increased risk of T2DM after gestational diabetes." (PMID 39509438, 2024). "Impaired insulin sensitivity or insulin secretion is widely recognized as the main underlying pathology of gestational diabetes mellitus." (PMID 38414896, 2024). "Vitamin D stimulates insulin production by preventing insulin deficiency, a central factor in the pathogenesis of gestational diabetes mellitus, and reduces pro-inflammatory cytokines present in the pre-eclamptic placenta." (PMID 39273635, 2024). "The rs1544410 SNP of the VDR gene has been associated with increased insulin secretion in women with post-gestational diabetes mellitus, suggesting a preventive role in developing post-gestational diabetes mellitus." (PMID 39408801, 2024). "TCF7L2 is an extensively studied genetic factor implicated in reduced insulin secretion and an increased risk of developing gestational diabetes mellitus (GDM)." (PMID 38694942, 2024). "For women with gestational diabetes who are deficient in Vitamin-D, Vitamin-D supplementation can improve their glycemic control and boost their insulin levels." (PMID 39281255, 2024). "Upregulated in Jamaican fruit bat cells, PTPRD, which is involved in insulin signaling and associated with gestational diabetes risk, also displayed high centrality in the Jamaican fruit bat." (PMID 38195585, 2024). "PTPRD is involved in insulin signaling and variants within this gene were found to be associated with gestational diabetes risk." (PMID 38195585, 2024). "•Ama Buildup: Per Ayurveda, the body's buildup of ama (toxins) can disrupt cellular metabolism, reduce insulin sensitivity, and heighten the risk of developing gestational diabetes." (PMID 39662422, 2024). "The inability of pregnant women to compensate for the physiologic hormone-driven increase in insulin resistance along with decreased insulin sensitivity results in hyperglycemia, causing the pregnant body to develop gestational diabetes problems." (PMID 38868299, 2024). "If a mother has gestational diabetes and becomes insulin resistant in the third trimester, her relative risk of serious cardiovascular problems is highest." (PMID 39840159, 2024). "Among them, myoinositol can reduce the risk of gestational diabetes by increasing insulin sensitivity, which was significantly up-regulated in the F1 vs. F8 comparison group." (PMID 39061849, 2024). "We observed that women who experienced complications during pregnancy had greater levels of maternal visceral fat, especially gestational diabetes, which was linked to metabolic risk factors including insulin resistance and arterial blood pressure." (PMID 36829423, 2023). "The CHarité AssessmeNt of GEstational Diabetes (CHANGED) Score contributes to the understanding of the risk factors for insulin dependency in gestational diabetes patients." (PMID 38002781, 2023). "Previous studies from our service analyzed the data on women with gestational diabetes to predict the risk of needing insulin, but the populations in these studies differ from the one we studied here." (PMID 37268897, 2023).